MIR4649 (microRNA 4649)
Synonyms: hsa-mir-4649; mir-4649
Gene: MicroRNA gene on chromosome 7 (44,110,849 to 44,110,912, forward strand). Ensembl gene ENSG00000284412.
Diseases named in the same sentence as MIR4649 in open-access papers:
MIR4649 is named in the same sentence as 1 disease in open-access papers, as found by Europe PMC text mining. Sharing a sentence is not in itself a finding about the gene and the disease.
MIR4649 shares sentences with these, for which no sentence is quoted: head and neck squamous cell carcinoma (1 paper).